ENSG00000258311 (novel protein)
Gene: Protein-coding gene on chromosome 12 (55,716,036 to 55,724,703, forward strand). Ensembl gene ENSG00000258311.
Genetic constraint (gnomAD): Loss-of-function variants: 13 observed, 16.74 expected, observed/expected ratio (o/e) 0.78, 90% interval 0.5 to 1.23. Missense variants: 181 observed, 155.87 expected, observed/expected ratio (o/e) 1.16, 90% interval 1.03 to 1.31. Synonymous variants: 75 observed, 60.92 expected, observed/expected ratio (o/e) 1.23, 90% interval 1.02 to 1.49.